EGFR (epidermal growth factor receptor)
Diseases named in the same sentence as EGFR in open-access papers (continued):
Sharing a sentence is not in itself a finding about the gene and the disease.
lung cancer (continued). "The aim of this study was to establish a radiomic model to predict the EGFR mutation status of lung cancer brain metastases." (PMID 35912248, 2022). "In particular, epidermal growth factor receptor-tyrosine kinase inhibitors (EGFR-TKIs) have been developed as targeted agents for patients with lung cancers harboring EGFR mutations." (PMID 35745617, 2022). "Of the 265 patients initially included in the study, the EGFR mutation status of 52 patients was available for both the primary lung cancer and the corresponding BMs." (PMID 35912248, 2022). "Other standards of care for lung cancer include inhibition of EGFR; however, resistance to treatment via mutation or the upregulation of other receptors is an ongoing problem." (PMID 36551663, 2022). "EGFR-TKI resistance developed in EGFR-mutated lung cancer cells by Col I absorption via macropinocytosis, while macropinocytosis inhibition reduced Col I absorption in PC-9 cells and restored their EGFR-TKI sensitivity." (PMID 36046825, 2022). "The Asian population has a high lung cancer burden, responsible for nearly 20% of cancer mortality, and it has the highest global rates of EGFR-mutated types." (PMID 36360466, 2022). "In lung adenocarcinoma, activated EGFR-mediated signaling causes the activation of many downstream signaling pathways that help in lung cancer cell proliferation, growth, and resistance to chemotherapies." (PMID 36080307, 2022). "In-frame deletions in exon 19 are the most frequently reported EGFR mutations in lung cancer patients present at a rate of around 46.3% to 76.2%, followed by L858R missense mutation in exon 21 present at a rate of 26% to 38% as reported by Noronha et." (PMID 36613084, 2022). "In lung cancer patients with EGFR gene mutations, tyrosine kinase inhibitors (TKIs) that target mutant EGFR genes are associated with a therapeutic advantage." (PMID 36530971, 2022). "The analysis of potential genomic biomarkers of immunotherapy in 1000 Chinese patients with cancer showed that lung cancer patients with EGFR mutations had significantly lower TMB than those with wild-type EGFR." (PMID 35172862, 2022). "Coincidentally, miR-147b was discovered to be the most upregulated miRNA in lung cancer cells resistant to osimertinib and EGFR mutations." (PMID 36386184, 2022). "RhoA and SRF also control the expression of several drug resistance and metastasis-associated genes in EGFR-mutant lung cancer cells." (PMID 36509758, 2022). "CtDNA is also routinely used as a predictive marker for some subpopulations such as EGFR‐mutated lung cancer for which EGFR inhibitors can be administered based on plasma analysis." (PMID 35122700, 2022). "Liquid biopsy identified nine (45%) de novo EGFR-T790M mutations during TKI-treatment follow-up in lung carcinoma." (PMID 36497340, 2022). "Especially, EGFR TKIs are demonstrated to have ability to prolong survival time of EGFR-mutated patients with lung carcinoma." (PMID 35031014, 2022). "With respect to histomorphology, our results show that the rate of EGFR mutations is highest (82.4%) in adenocarcinoma, followed by squamous cell carcinoma (7.9%) and other types of lung carcinomas (10.27%)." (PMID 36613084, 2022). "HCSC plays an all-around role in the treatment of lung cancer and is expected to overcome the resistance of EGFR-TKI caused by the T790M mutation." (PMID 34239587, 2021). "A number of oncogenic driver mutations have been identified in lung cancer with the EGFR and KRAS mutations as the most prevalent and with significant clinical implications." (PMID 33652978, 2021). "On the opposite, our team has recently reported that the loss of sortilin promoted lung cancer cell proliferation, in relation with the epidermal growth factor receptor (EGFR) signalling efficiency." (PMID 33325631, 2021).
lung cancer (continued). "The most illustrative example is the detection of targetable mutations in EGFR-mutated lung cancer patients." (PMID 34440680, 2021). "EGFR mutations were detected in genomic DNA obtained from either tumor tissues or malignant pleural effusions from eleven lung cancer patients using genetic tests by a certified laboratory." (PMID 33846488, 2021). "This was owing to highly frequent EGFR in CSF, which had been verified by a previous study that lung cancer patients with EGFR mutations had significantly lower TMB values than those with wild-type EGFR." (PMID 34642306, 2021). "Approximately 10% of non‐small cell lung cancers (NSCLCs) that harbor epidermal growth factor receptor (EGFR) gene mutations have in‐frame insertions in exon 20 of the EGFR gene." (PMID 33710795, 2021). "For example, the authors have recently reported that epidermal growth factor receptor (EGFR) mutated lung cancer BMs occurred more frequently in the caudate nucleus, cerebellum, and temporal lobe than those with an EGFR exon 19 deletion." (PMID 34276994, 2021). "Each study used EGFR-mutated lung cancer cell lines to identify candidate essential molecule(s)/pathway(s) for DTC induction by establishing DTCs via short-term exposure to EGFR TKIs or by using shRNA-, siRNA-, or CRISPR/Cas9-mediated screening." (PMID 34202566, 2021). "Patients with lung cancer with sensitizing-EGFR mutations clinically benefit from EGFR-tyrosine kinase inhibitors (TKIs) as first-line therapies." (PMID 34663810, 2021). "MET has been proposed as one of the driving oncogenes in lung cancer and the cause of drug resistance to EGFR TKIs." (PMID 33917539, 2021). "We provide a valuable resource of EGFR-mutant lung cancer–specific neoepitopes as well as tumor-associated immunopeptides for possible design of precision immunotherapy and cancer vaccines." (PMID 34391887, 2021). "Recent advances in the clinicogenomics of lung cancer have uncovered the role of epidermal growth factor receptor (EGFR) mutations in a significant proportion of NSCLC patients." (PMID 34055528, 2021). "Pharmacologically inhibiting EGFR by specific tyrosine kinase inhibitors (TKIs) has been proven highly successful in treating lung cancer patients harboring EGFR-activating mutations." (PMID 33467099, 2021). "Along the same lines, a previous study observed a similar distribution of EGFR mutations among early-stage and metastatic EGFR+ lung cancers, which is also consistent with the notion that EGFR alterations represent “early events” during lung carcinogenesis." (PMID 33898315, 2021). "Epidermal growth factor receptor (EGFR)-mutated lung cancer constitutes a major subgroup of non-small cell lung cancer (NSCLC) and osimertinib is administrated as first-line treatment." (PMID 33461557, 2021). "The Pan-Cancer Cell-Free Assay can be applied to detect EGFR mutations in advanced lung cancer patients, although follow-up studies will be needed to evaluate the analytical validity for other types of genes and aberrations using clinical samples." (PMID 34199654, 2021). "A study on 110 patients evaluated if MR radiomics from brain metastasis originated from lung cancer was shown to associate with EGFR, ALK and KRAS mutations and reported excellent model performances for all three tissue biomarkers (AUC > 0.9, LOOCV)." (PMID 34208595, 2021). "Nevertheless, in the Middle Eastern region the only study of lung cancer-specific of EGFR mutation to date involves the levant population, the EGFR mutation was founded in 15.6% of NSCLC patients, which is lower than ours." (PMID 34963835, 2021). "A retrospective analysis from the Shizuoka Lung Cancer Mutation Study found that among 705 enrolled patients, 102 lung adenocarcinoma patients carried the typical EGFR L858R exon 21 mutation." (PMID 33869038, 2021).
lung cancer (continued). "A pilot study indicated that plasma levels of linoleic acid were significantly higher in lung cancer patients with EGFR mutations and identified linoleic acid as a potential biomarker for the early detection of lung cancer." (PMID 34434895, 2021). "In contrast, both EGFR‐mutated lung cancer cells NCI‐H1975 and HCC827 had higher expression levels for LncRNA GAS5." (PMID 33433063, 2021). "Several lung cancer patients with poor prognosis exhibit EGFR overexpression and hyperactivation due to EGFR mutations." (PMID 34445110, 2021). "Targeted inhibition of EGFR with a small molecule kinase inhibitor has significant clinical benefits in lung cancer with EGFR mutations." (PMID 34369236, 2021). "Epidermal growth factor receptor (EGFR) inhibitors are a highly effective treatment for lung cancer, one of the leading causes of death worldwide." (PMID 34574036, 2021). "Epidermal growth factor receptor (EGFR) tyrosine kinase inhibitors (TKIs) are a first-line treatment for patients with nonsmall-cell lung cancer harboring EGFR mutations." (PMID 34306720, 2021). "Epidermal growth factor receptor (EGFR) mutations are the most common driver gene mutations in lung cancers and are found in approximately 50% of lung adenocarcinomas in East Asians and in approximately 15% in Caucasians." (PMID 34202566, 2021). "A recent clinical trial shows that a proportion of lung cancer patients carrying the EGFR T790M mutation develop resistance to osimertinib." (PMID 33741979, 2021). "In this review, we first provide a discussion of EGFR-mutated lung cancer and the efficacy of available EGFR TKIs in the clinical setting against both common and rare EGFR mutations." (PMID 34202748, 2021). "Although EGFR TKIs became the standard of care in patients with EGFR-mutated lung cancer, resistance almost inevitably develops." (PMID 34202748, 2021). "We provide evidence that CDCA3 levels are increased in EGFR mutant lung cancer and these levels are associated with sensitivity to TKIs." (PMID 34572879, 2021). "The cobas test is based on allele‐specific real‐time PCR, and the detection limit has been reported to be 0.025%−0.15% by analysis using fragmented DNA isolated from lung cancer cell lines bearing EGFR mutations." (PMID 33982444, 2021). "In this paper, to further validate that, we performed differential expression analysis on responsive genes and their associated methylation sites in EGFR inhibitor-sensitive and -resistant lung cancer cell lines." (PMID 34356665, 2021). "For instance, the epidermal growth factor receptor (EGFR) gene is one of the most frequently mutated genes in lung cancer, particularly in non-small cell lung adenocarcinoma." (PMID 34938205, 2021). "All serial patients with lung cancer tested for EGFR mutations with CDx tests between February 2014 and February 2016 at the Cancer Institute Hospital of the Japanese Foundation for Cancer Research (JFCR) were enrolled in this analysis." (PMID 33528892, 2021). "In this work, we compare the single-cell transcriptome of tumor-infiltrating immune cells between the two molecular subtypes of lung cancer and seek key cell subsets and their molecular features associated with EGFR mutation." (PMID 34663810, 2021). "Of note, in lung cancer, the mutations in EGFR and KRAS (the two most common ones) are considered mutually exclusive." (PMID 34440587, 2021). "Lastly, for lung cancer patients that develop metastases to the central nervous system (CNS), detection of EGFR mutations in the cerebrospinal fluid (CSF) has been proven to be more efficient than plasma to evaluate PFS." (PMID 34440110, 2021). "Previous studies mainly used the clinical characteristics, conventional metabolic parameters, and radiomics features of 18F-FDG PET/CT to predict EGFR mutation status in patients with lung cancer, such as tumor margin, CEA level, smoking history, and SUVmax." (PMID 34367993, 2021).
lung cancer (continued). "Although EGFR-TKIs are the key drug for treating EGFR mutation-positive lung cancer, cytotoxic anticancer agents remain an important treatment option." (PMID 34831415, 2021). "Koo co-delivered plasmids coding Cas9 protein and epidermal growth factor receptor (EGFR) mutation-specific sgRNA by AV to treat the EGFR-mutated lung cancer." (PMID 34683943, 2021). "Mutation of the EGFR gene in exon E18 was significantly related to sample type, pathologic type, lung cancer stage, and treatment method." (PMID 34217313, 2021). "The oncogenic mutation of tumour-inducing genes, such as KRAS and EGFR or their surrogates, is prevalent in human lung cancers." (PMID 34381028, 2021). "This trial aimed to assess the efficacy of afatinib in treatment‐naïve patients with lung cancer harboring epidermal growth factor receptor mutations (EGFRm, exon 19 deletions or exon 21 point mutations) detected based on ctDNA." (PMID 33270375, 2021). "Non-small cell lung cancer (NSCLC) accounts for approximately 85% of lung cancer cases, with few patients carrying driver mutations in the gene encoding for epidermal growth factor receptor (EGFR)." (PMID 34202063, 2021). "Our new model fully recapitulates the treatment response observed in patients with EGFR-mutated lung cancer who relapse after osimertinib." (PMID 34298655, 2021). "The prevalence of EGFR germline mutation in Chinese patients with lung cancer was 0.2% (64/31,906), which was higher than that found in a previous study." (PMID 34869019, 2021). "A total of 513 advanced NSCLC patients who were tested for EGFR mutation status were included in the final study out of 1510 lung cancer patients." (PMID 34836017, 2021). "Targeting activating mutations in the tyrosine kinase epidermal growth factor receptor (EGFR) represents a success story in the treatment of lung cancer, a very commonly diagnosed malignancy that remains the leading cause of cancer-related mortality." (PMID 34202748, 2021). "The R521K variant has also been described as being associated with cancer severity in EGFR-expressing tumors, like gliomas, lung cancer and breast cancer." (PMID 33874989, 2021). "For example, the mutation rate of EGFR in lung cancer in European and American countries is about 15%, while that in China is more than 50%31,32." (PMID 33707577, 2021). "Regarding genetic factors, many studies have demonstrated that gene mutations in EGFR are strongly linked to lung cancer through the disruption of intracellular signaling pathways." (PMID 33705793, 2021). "For molecular-targeted therapies, some reports have shown that ctDNA is useful for evaluation of treatment response and resistance, such as RAS mutation in colorectal cancer or EGFR mutations in lung cancer, known as targeting driver genes." (PMID 34174931, 2021). "Among studies of DTCs in EGFR-mutated lung cancers, a few suggested a possible “preference” for drug tolerance mechanism(s) in cell lines." (PMID 34202566, 2021). "Many risk factors are currently known to cause lung cancer, among which mutations in the epidermal growth factor receptor (EGFR) gene have been shown to be related to more than 60% of NSCLCs." (PMID 34948746, 2021). "The rapid development of an optimal treatment for EGFR-mutated lung cancer will require a better understanding of the underlying molecular mechanisms of the drug insensitivity of DTCs." (PMID 34202566, 2021). "The US Food and Drug Administration (FDA) has approved a series of EGFR-TKIs, including gefitinib, erlotinib, afatinib, dacomitinib, and osimertinib, as the first-line treatment of advanced lung cancer with EGFR mutations." (PMID 34575576, 2021). "EGFR-D770>GY and other EGFR insertions with a G770 equivalence were identified at a frequency of 3.96% in separate cohorts of EGFR exon 20 insertion mutated lung cancer (n = 429)." (PMID 34944068, 2021). "Epidermal growth factor receptor (EGFR)-mutant lung cancers have a high risk of developing brain metastases (BM)." (PMID 34847914, 2021).
lung cancer (continued). "Mutations in exons E19 and E21 represented the vast majority (87%) of all observed EGFR gene mutations in lung cancer patients, which is consistent with another study." (PMID 34217313, 2021). "The association between EGFR and radiomics in lung cancer was the most frequently investigated (n = 26)." (PMID 34208595, 2021). "The biology underlying the lower clinical response rates to immunotherapy in lung cancer with EGFR mutations has been investigated in several studies and is thought to be related to the higher diversity and lower clonality of patients with EGFR mutations." (PMID 33777727, 2021). "Taking as an example lung adenocarcinoma accounting for the highest proportion of lung cancer, the rate of functional driver gene mutations including EGFR, KRAS and rearrangement of ALK or ROS1, is approximately 60%." (PMID 34814861, 2021). "In this review we discuss currently approved TKIs for the targeted management of EGFR-mutated lung cancer." (PMID 34202748, 2021). "For instance, approximately 80–90% of patients with EGFR-mutated, non–small cell lung cancer have either deletions in exon 19 or substitutions of leucine for arginine (L858R) in exon 21 of the EGFR gene." (PMID 33572326, 2021). "A recent cohort study from Taiwan has shown that statins are associated with increased survival in lung cancer patients treated with epidermal growth factor receptor-tyrosine kinase inhibitors (EGFR-TKIs) and exert synergistic anti-cancer effects." (PMID 34303383, 2021). "EGFR TKI has been successfully employed in the clinic, especially in lung cancer patients who have EGFR mutations." (PMID 34368128, 2021). "Other authors demonstrated that ddPCR provides high concordance rates of EGFR mutations between PF supernatants and cell pellets of lung cancer patients." (PMID 34199799, 2021). "The study showed that ANXA1 plays critical roles in chemosensitivity to Osimertinib in lung cancer cells with EGFR mutations." (PMID 34439260, 2021). "Development of a methodology capable of more safely collecting tumor samples and more accurately detecting EGFR mutations in patients with lung cancer is needed." (PMID 33757469, 2021). "EGFR gene amplification causes numerous types of cancers, including breast cancer, colorectal cancer, lung cancer, and oral cancer." (PMID 34298758, 2021). "A LB at diagnosis in late stage lung cancer has been developed using mostly targeted sequencing, notably for the detection of EGFR mutations or ALK/ROS1 fusions." (PMID 33922637, 2021). "Among all 142 clinical trials, nine (6%) were influenced by disease prevalence among certain racial-ethnic population mostly because of epidermal growth factor receptor–activating mutations and Asian populations in lung cancer." (PMID 33974825, 2021). "Ongoing research on targeted anticancer agents has revealed the mechanisms of various targetable pathways associated with lung cancer (e.g., EGFR, PI3K/AKT/mTOR, RAS-MAPK, and JAK/STAT)." (PMID 34393769, 2021). "Our study cohort was 22% African American, which is important given the paucity of data that exists which addresses racial disparities among patients with EGFR mutated lung cancer." (PMID 33804721, 2021). "For instance, EGFR signaling within lung cancer cells can jeopardize antitumor immunity, which is caused by the transferral of EGFR to host macrophages by exosomes, which resultantly suppresses the innate antiviral immunity." (PMID 33855679, 2021). "Asia has the highest prevalence of epidermal growth factor receptor (EGFR) mutations in patients with non‐small cell lung cancer (NSCLC)." (PMID 34374490, 2021). "What clinicopathologic and genomic features are associated with risk for recurrence in patients with resected non–small cell lung cancer (NSCLC) harboring epidermal growth factor receptor (EGFR) alterations?" (PMID 34739062, 2021).